IL33 (interleukin 33)
Diseases named in the same sentence as IL33 in open-access papers (continued):
Sharing a sentence is not in itself a finding about the gene and the disease.
melanoma (continued). "Furthermore, we found that IL-33 is mainly derived from stromal cells in the metastasis sub-cohorts, and from epithelial cells/keratinocytes in the primary melanoma sub-cohort." (PMID 33621202, 2021). "Furthermore, in the B16.OVA melanoma model, systemic administration of IL-33 combined with injection of dectin-1-activated bone marrow-derived DC induced activation and PD-1 expression in OVA-specific CD4+ T cells." (PMID 33329534, 2020). "Notably, in IL-33 treated mice we found tumor-infiltrating EO primarily in necrotic areas of melanoma tissue, with evidence of granule protein polarization towards tumor apoptotic cells." (PMID 31717819, 2019). "We previously reported that IL-33-activated EO were superior at killing target melanoma cells." (PMID 31717819, 2019). "Similarly, administration of recombinant IL-33 inhibited the growth of established melanoma tumors by activating myeloid dendritic cells and tumor associated CD8+ T cells." (PMID 31231372, 2019). "Similarly, increased frequencies of CD107a+IFN-γ+ NK cells were observed following exogenous administration of IL-33 in spleens and tumors of B16 melanoma-bearing mice." (PMID 30483263, 2018). "Indeed, IL-33 functions as a promoter to memory T cell immunity in transgenic melanoma mice, thereby mediating a microenvironment that favors tumor rejection." (PMID 30619376, 2018). "IL-33 could restrict tumor growth and inhibit pulmonary metastasis in melanoma-bearing mice through eosinophils." (PMID 29568370, 2018). "However, some studies also propose a possible protective role of the IL33/sST2 axis in melanoma, breast, colorectal, prostate and hepatocellular cancer tumor models by stimulating antitumor immunity." (PMID 30426271, 2018). "Eosinophils and DCs may also mediate the anti-melanoma effects of exogenous IL-33." (PMID 40236667, 2024). "It has also been reported that in melanoma and colon cancer models IL-33 can effectively promote the function of immune cells to inhibit cancer cells from metastasizing, which suggests that the antitumor effect of IL-33 may also be predominant in lung cancer." (PMID 35634336, 2022). "Moreover, whether TME IL-33 alone or in combination with additional unidentified stimuli induces the high levels of ILC2 TNF-α in our melanoma model requires further exploration." (PMID 34531874, 2021). "Systemic administration of recombinant IL-33 protein could inhibit growth of established tumors in transplant and de novo melanoma tumorigenesis models through inducing CD8 T cell expansion and IFN-γ production, as well as through restoring dendritic cell activation and maturation." (PMID 29568370, 2018). "Likewise, in EG7 lymphoma, B16, and inducible BrafV600EPTEN melanoma models exogenous IL-33 activated myeloid DCs within the tumor microenvironment increasing antigen cross-presentation and restoring anti-tumor T cell activity in a ST2, MyD88, and STAT1-dependent manner." (PMID 30483263, 2018). "By contrast, pre-exposure to DAC/IL-33 unleashed the anti-tumor response to PD-1 mAb in melanoma-bearing mice, as shown by significant tumor growth delay and ameliorated survival with respect to DAC/IL-33 and control." (PMID 40317004, 2025). "We analyzed the immune infiltrate in melanoma-bearing mice three days after the last cytokine administration and found that DAC/IL-33 treatment significantly promoted the recruitment of immune (CD45+) cells in the tumor." (PMID 40317004, 2025). "In melanoma-bearing mice, a single injection of DAC (i.p.)in combination with five intratumoral (i.t.)injections of IL-33 reduced tumor growth significantly, with respect to control mice, although not with respect to mice exposed to single treatment." (PMID 40317004, 2025). "Multicellular spheroids, organ-on-chip technology and in vivo models were used to test the anti-tumor effects of IL-33 combined with DAC against mouse and human melanoma." (PMID 40317004, 2025).
melanoma (continued). "We show that the combination of DAC with IL-33 remodels the TME and ameliorates immunotherapy response to PD-1 blockade in melanoma-bearing mice." (PMID 40317004, 2025). "We found significantly increased expression of both IL33 and its receptor ST2 in melanoma tissues from WT mice exposed to DAC treatment with respect to untreated controls." (PMID 40317004, 2025). "IL-33 also recruits eosinophils to the lung via ST2, preventing pulmonary metastasis after intravenous melanoma cell injection." (PMID 40136652, 2025). "For example, treatment of α-IL-33 and α-ST2L suppresses type 2 ILCs, inhibiting melanoma progression and reversing chemoresistance." (PMID 38778059, 2024). "Following IL-33 stimulation, ILC2s have been shown to up-regulate the ectoenzyme CD73, of which the product adenosine is well known to be enriched within the melanoma TME and to suppress NK cell cytotoxicity." (PMID 36765891, 2023). "Depending on the active alarmins within the TME, PD-1 expression is increased in the corresponding ILC subset (exogenous IL-33 in the case of ILC-2s, and melanoma tumor cell-derived lactate in case of T-bet+ ILCs)." (PMID 37098069, 2023). "Eosinophils activated by IL‐33 induced the recruitment and activation of CD8+ T cells and natural killer cells in melanoma‐bearing mice." (PMID 37669914, 2023). "In the case of the IL1RL1 gene, which codes a specific receptor (ST2) for IL-33 interleukin, it was reported that the IL-33/ST2 axis increases the migration and invasion of melanoma cells through ERK1/2 signaling." (PMID 37240247, 2023). "In a lung metastatic murine model by intravenous injections of B16-F10 melanoma cells or Lewis lung carcinoma, ILC2s, eosinophils, CD8+ T cells and NK cells were activated and tumor-infiltrating by IL-33 overexpression or IL-33 treatment." (PMID 37508545, 2023). "Both JUP and DSP were identified to be upregulated in melanoma cell lines, where they significantly increase tumor burden, VEGF-A, reduced IL-33, and angiogenesis, thus emphasizing their PT roles." (PMID 37834160, 2023). "While we provided evidence that melanoma cells can produce both TGF-β and IL-1β, IL-33 was undetectable in supernatants from both A375 and RPMI-5971 cells." (PMID 35669782, 2022). "In vitro, we show that melanoma cell supernatants and tumor microenvironment (TME) mediators such as TGF-β, IL-33, and IL-1β induce some of the changes found in MAMCs and significantly modulate C3 expression and activity in MCs." (PMID 35669782, 2022). "In contrast, treatment of mice with IL-33 has also been shown to decrease metastasis in murine models of ID8 ovarian cancer peritoneal metastasis and B16 melanoma pulmonary metastasis." (PMID 35756626, 2022). "ILC2s in mice melanoma express high levels of ST2 and PD-1, and co-administration of IL-33 with PD-1 blockade therapy can significantly improve the antitumor effect mediated by ILC2s.." (PMID 35720302, 2022). "In both in vitro and in vivo experimental settings, IL‐33 acted as an immunosuppressive cytokine by activation of macrophages, which successively inhibited TIL‐mediated specific killing of human primary melanoma cells." (PMID 34486239, 2021). "IL33 has also been shown to promote the infiltration of CD8+ T cells into tumor cells and suppress tumor growth in a melanoma model." (PMID 35011007, 2021). "One group reported that IL-33-stimulated DC expand a population of cytotoxic IL-9 producing CD8+ T cells, termed Tc9, endowed with potent anti-tumor activity in melanoma-bearing mice." (PMID 33329534, 2020). "Recently, our group reported that mouse basophils stimulated with IL-33 up-regulate the expression of granzyme B and of the degranulation marker CD63 and induce melanoma cell killing in vitro." (PMID 33329534, 2020). "We, therefore, performed in vitro experiments by co-incubating eosinophils with CT26 cells and showed IL-33 dependent cytotoxic properties of eosinophils, corroborating data from studies in human and murine CRC and melanoma." (PMID 32923137, 2020).
melanoma (continued). "IL-33 administration in tumor-bearing mice activated DC and increased Ag cross-presentation to CD8+ T cells in melanoma and acute myeloid leukemia (AML) models." (PMID 33329534, 2020). "In a murine model of melanoma, in vivo expansion of innate IL-5–producing ILC2 cells following systemic IL-33 injection played an important role for eosinophil recruitment and metastasis control." (PMID 30483263, 2018). "In other studies using mouse models of lung metastasis, transgenic expression of IL-33 in Lewis Lung carcinoma (LLC) and B16 melanoma cells attenuated tumor metastasis." (PMID 30205617, 2018). "Exposure of melanoma cells to IL-33 did not interfere with the formation of either mouse or human melanoma spheroids." (PMID 40317004, 2025). "Flow cytometry analysis confirmed significantly higher percentages of PD-1-expressing CD4 and CD8 T cells in melanoma tumors from mice exposed to the combo DAC/IL-33 treatment, but not from those receiving single treatments, with respect to untreated animals." (PMID 40317004, 2025). "Intriguingly, the observation that DAC positively modulates the expression of both IL-33 and ST2 in the TME of melanoma-bearing mice may suggest an epigenetic control of this axis." (PMID 40317004, 2025). "Elevated levels of IL‐33 in primary melanoma samples appeared to not correlate with patient prognosis, while metastatic samples correlated with prolonged overall survival and progression‐free survival." (PMID 38775220, 2024). "Although GM-CSF alone also induces CD103+ cDC1s upon in vivo injection or treatment of FL-BMDCs61, it does not inhibit tumor growth, unlike IL-33-induced tumor suppression in lymphoma or melanoma models." (PMID 38825642, 2024). "While IL-33 promotes tumor progression in some cancer types, such as breast or colon cancer, some studies have shown it to increase CD8 + T cell infiltrations and suppress melanoma cell growth or activate NK cells." (PMID 37587450, 2023). "Likewise, IL-33 and anti-PD-1 combination therapy was recently shown to unbridle anti-tumor immunity mediated by an ILC2-eosinophil axis in a murine model of melanoma." (PMID 35756626, 2022). "However, the cell culture supernatants from A375 and RPMI-7951 melanoma cell lines contain TGF-β and IL-1β and also profoundly increase the production of IL-1β and IL-33 in MCs." (PMID 35669782, 2022). "In various malignant TMEs, including those fostered by surrounding melanoma, immunosuppressive cytokines, such as TGF-β, and the pro-inflammatory mediators of the IL-1 family, IL-1β and IL-33, have emerged as key facilitators of tumor growth, angiogenesis, and modulators of local immune responses." (PMID 35669782, 2022). "In the mouse B16 melanoma model, administration of IL-33 decreased accumulation of MDSCs in the spleen and TME, suggesting IL-33 may counteract MDSCs expansion and function relying on the tumor type." (PMID 34209038, 2021). "In another melanoma model, IL-33 induced proliferation of innate IL-5-producing non-T cells upon tumor invasion, and the regulation of eosinophils by these IL-5-producing cells appeared to be critical to limit tumor metastasis." (PMID 34209038, 2021). "Inhibition of IL‐33 and MMP‐9 restore the TIL‐mediated killing effects in melanoma cells." (PMID 34486239, 2021). "Collectively, we conclude that IL-33 catered by Cxcl13-Cre+ FSCs to CD8+ T cells in the TME sustains T cell effector differentiation and prevents T cell exhaustion, hence enabling curative melanoma treatment by LCMV-based viral vectors." (PMID 34354077, 2021). "In the primary melanoma sub-cohort, the expression level of IL-33 has no prognostic value in terms of overall survival (OS) or progression-free survival (PFS)." (PMID 33621202, 2021). "We next assessed whether IL-33 induced the expression of eosinophil-attracting chemokines (CCL11, CCL24, CCL26, and CCL5) in melanoma cells and found significant up-regulation of CCL5 and CCL24." (PMID 31717819, 2019).
melanoma (continued). "Of note, when the device contained Matrigel alone (without melanoma cells), addition of IL-33 failed to elicit the migration of EO, indicating that IL-33 triggered a chemotactic response via stimulation of tumor cells." (PMID 31717819, 2019). "In addition, IL-33 activated eosinophils in vitro enhancing CD11b, CD69, and granzyme B expression and activating cytotoxic functions against melanoma cells." (PMID 30483263, 2018). "Expression of IL-33 by tumor cells promotes CD8 T cell-mediated anti-tumor responses in various cancer models, including colorectal cancer, pancreatic ductal adenocarcinoma (PDAC), melanoma and breast cancer and is required for immune checkpoint blockade (ICB) efficacy." (PMID 40317004, 2025). "In contrast, IL-33 did not exert any direct action on melanoma cells and its combination with DAC did not further decrease tumor growth in either 2D or 3D settings, corroborating that the antitumor functions of this cytokine are attributable to the stimulation of immune response." (PMID 40317004, 2025). "In marked contrast, when ST2−/− spleen cells were assayed in the chip for their migratory response to treated melanoma cells, no significant displacement was observed towards either right (DAC/IL-33) or left (single treatment or no treatment) melanoma chambers." (PMID 40317004, 2025). "IL-33 was not detectable in melanoma cell culture supernatants." (PMID 35669782, 2022). "Thus, the fact that multiple cytokines synergize in modulating C3 expression would explain why TGF-β, IL-33, and IL-1β activity blockade did not fully inhibit the expression of C3 in MCs treated with melanoma cell culture supernatants." (PMID 35669782, 2022). "This may explain why IL-33 does not have effects on immune modulation or prognostic values in the primary melanoma sub-cohort." (PMID 33621202, 2021). "Furthermore, IL-33 EO, unlike IL-5 EO, interfered with tumor 3D-spheroid formation in vitro and slowed tumor outgrowth in vivo when co-injected with B16 melanoma cells into syngeneic mice." (PMID 31717819, 2019). "Of relevance, we could translate to the human system the findings that EV from IL-33-activated human eosinophils induced transcriptional reprogramming of cell cycle and EMT-related genes resulting in anti-proliferative effects on A375P melanoma cells in standard and 3D cultures." (PMID 39061080, 2024). "However, IL-33 is not a prognostic factor in the primary melanoma sub-cohort." (PMID 33621202, 2021). "In apparent contrast with these findings, we found that IL-33 alone poorly induced PD-1 in the TME and did not ameliorated PD-1 blockade in melanoma-bearing mice." (PMID 40317004, 2025). "In our experiments, we found higher expression levels of the IL1RL1 gene in melanoma cell lines with increased invasion after HHSEC-CM treatment, but we have not observed any IL-33 expression in the hepatic endothelial cells." (PMID 37240247, 2023). "However, the expression level of IL-33 in human melanoma samples is uncorrelated or even negatively correlated to the abundance of melanocytes, indicating that melanoma cells may not be the source of IL-33." (PMID 33621202, 2021). "It should be noted, however, that the expression of IL-33 and SIGLEC8 has been found to demonstrate different survival prognosis in diverse types of cancer, with better survival outcomes in melanoma patients but not in those with pancreatic adenocarcinoma and lung squamous cell carcinoma." (PMID 34691082, 2021).
Arthritis (62 papers, 2006 to 2026). Inflammation of a joint. "Secondly, in the autoantibody-induced arthritis animal models, the introduction of IL-33 was associated with significantly greater clinical scores for arthritis." (PMID 38666958, 2024). "In further support for pathogenic functions of IL‐33 cytokines in arthritis, IL‐33 signalling blockade was shown to attenuate experimentally induced autoimmune arthritis." (PMID 32566227, 2020). "Concomitant ablation of MyD88 reversed the effects of mast cell-specific A20 loss during arthritis induction to a large extent, indicating essential roles for IL-33, TLR ligands, and/or IL-1β." (PMID 24453940, 2014). "Tissue damage or physical stress during the early stages of arthritis development cause local release of endogenous TLR ligands or alarmins such as IL-33." (PMID 24453940, 2014). "Most recently, IL-33 has been associated with allergic airway inflammation and arthritis in experimental animal models." (PMID 23634226, 2013). "Recent studies have implicated IL-33 in the activation of synovial MCs in murine arthritis." (PMID 23071771, 2012). "Recently, IL-33 has been linked to arthritis and the recruitment of neutrophils into the joint." (PMID 22028860, 2011). "In summary, there is clinical evidence that Pso, especially if associated with arthritis and a more advanced age, is associated with hypovitaminosis D, inflammation, and OP, and these factors might shift the effect of IL-33 from osteoprotective to proinflammatory and osteoclastogenic." (PMID 33488605, 2020). "Recent studies have identified the mesenchymal-derived cytokine IL-33 as a potent direct activator of MCs, as well as regulator of their effector phenotype, and have implicated this activity in the ability of mast cells to contribute to murine experimental arthritis." (PMID 23071771, 2012). "Clinically, IL-33 exacerbates arthritis in collagen-induced models, while blockade of the IL-33/ST2 axis with soluble ST2 or neutralizing antibodies reduces joint inflammation and damage." (PMID 41127878, 2025). "A potential link between IL-33 and arthritis has long been suggested, primarily on the basis of correlations between disease severity and IL-33 levels in the synovium, synovial fluid, and circulation." (PMID 41087719, 2025). "To further validate the role of IL-33 in RA, we performed validation experiments using a collagen antibody-induced arthritis (CAIA) mouse model." (PMID 39617790, 2024). "The role of IL-33 and NETs in RA progression was further investigated using a collagen antibody-induced arthritis (CAIA) mouse model." (PMID 39617790, 2024). "The inflammation score was first calculated, and we found that the TLR9 antagonist attenuated IL-33-induced arthritis in CAIA mice." (PMID 39617790, 2024). "IL-10 restricts the polarization of M1 macrophages, blocks the IL-33/ST2 axis during arthritis, and inhibits neutrophil recruitment, matrix metalloproteinases activity, edema, and pain." (PMID 37388729, 2023). "In view of other IL-1 cytokines, these results are in marked contrast with the critical role of IL-1β in the development of K/BxN STA, whereas both IL-33 and IL-36 were devoid of any effect in this model of arthritis." (PMID 37415987, 2023). "Studies have shown that IL-33 and ST2 were abnormally expressed in RA, SLE, SSc, and IBD, and the use of anti-ST2 antibodies reduced the production of IFN-γ, IL-17 and arthritis damage in mice, which indicated the potential role of IL-33 in AIDs." (PMID 37859999, 2023). "While mice deficient in the IL-33 Receptor, ST2, exhibited attenuation of arthritis, the severity of arthritis in the IL-33 knockout mice was similar to wild-type control mice." (PMID 35163028, 2022). "Key type 2 cytokines, like interleukin (IL)-4 and IL-13, but also others such as IL-5, IL-9, IL-25, and IL-33, exert regulatory properties on arthritis, dampening inflammation and inducing resolution of joint swelling." (PMID 35163028, 2022).